BECN1 (beclin 1)
Diseases named in the same sentence as BECN1 in open-access papers (continued):
Sharing a sentence is not in itself a finding about the gene and the disease.
breast carcinoma (continued). "In a pilot study, the culture of breast cancer MDA-MB-231 and BT-549 cells under normal conditions and transfection of the Beclin-1 gene resulted in inhibited cell growth and proliferation." (PMID 38315272, 2024). "The loss of CTNNA1 releases the suppression of the NF-κB pathway in breast cancer, while a CTNNA1 deletion attenuates the tumor suppressive effect of Beclin-1." (PMID 36741258, 2023). "Although the BECN1 gene is not considered a highly mutated gene in cancer (0.5% of all cancers), its monoallelic deletion can be seen in approximately 40% to 75% of ovarian, prostate, and breast cancers, which is why it is described as a “haploinsufficient tumor suppressor” gene." (PMID 36760166, 2023). "Black phosphorus quantum dots (QDs) disguised with a platelet membrane provided Hederagenin (HED) in breast tumor therapy (MCF-7 cells), and these HED-loaded QDs increased Beclin-1 and LC3-II to enhance the HED’s antitumor efficacy against breast cancer." (PMID 36766800, 2023). "Among human breast cancer samples excluding HER2-enriched tumors, tumors with overexpression of WNT-related genes and a low mRNA level of BECN1 present a poorer prognosis, and they are primarily TNBC." (PMID 37190065, 2023). "Another study observed that H19 was overexpressed in tamoxifen-resistant breast cancer cells, and the knockdown of lncRNA H19 abrogated autophagy by decreasing LC3-II and Beclin-1 levels." (PMID 36899946, 2023). "We have previously reported that carnosol induced a ROS-dependent beclin-1 independent autophagy and apoptosis in MDA-MB-231 breast cancer cells." (PMID 35712465, 2022). "Using multiple HER2+ breast cancer cell lines, Levine lab showed that HER2 and BECN1 interact, and that such interaction is dependent on the HER2 activity, as a kinase-dead mutant of HER2 failed to co-immunoprecipitate with BECN1." (PMID 35832792, 2022). "For example, elevated levels of Beclin-1 (Atg6) and LC3-II (Atg8) were identified in TAM-resistant MCF-7 breast cancer cells as compared to the antiestrogen-sensitive parent cells." (PMID 36077830, 2022). "Top-ranked Stem.Sig genes, such as EMC3, BECN1, VPS35, and PCBP2, showed improved immune response after knockout in melanoma, renal carcinoma, breast carcinoma, and colon adenocarcinoma from multiple CRISPR datasets." (PMID 35488273, 2022). "There is evidence that Beclin-1 (BECN1) acts as a suppressor of cancer and is involved in improving autophagy with lysosomal degradation; its expression levels are reduced in mammary carcinomas, particularly TNBC." (PMID 36059650, 2022). "BECN1-GFP isoforms (wt, α, β, or γ) were transiently expressed in the human breast cancer cell line MDA-MB231." (PMID 36008963, 2022). "Another investigation using breast cancer stem cells revealed that rottlerin treatment increases the expression of ATG12, BECN1 and LC3 proteins." (PMID 36497321, 2022). "Autophagy proteins, such as Beclin-1 and LC3A/B were found over-expressed in TNBC cells compared to the other breast cancer subtypes, and this expression appeared correlated with tumour progression and poor outcome in TNBC." (PMID 35761360, 2022). "Meanwhile, in the basal-like and HER2-enriched breast cancer subtypes TFEB and Beclin-1 seem to have a higher H-score than in the luminal molecular subtypes." (PMID 34663249, 2021). "Regorafenib was demonstrated to possibly exhibit antitumor activity on a breast cancer cell line via, at least in part, modulation of the P2X7/HIF-1α/VEGF, P2X7/P38, P2X7/ERK/NF-κB, and P2X7/beclin 1 signaling pathways." (PMID 34940128, 2021).
breast carcinoma (continued). "This retrospective study analyzes the expression of TFEB, CARM1, SIRT1, and Beclin-1 and the methylation of PITX2 in breast carcinoma." (PMID 34663249, 2021). "In the breast cancer cell line, MCF-7, which is estrogen receptor-positive and resistant to 4-hydroxytamoxifen (4-OHT), inhibition of autophagy with siRNAs for Atg5 and Beclin-1 increased sensitivity to tamoxifen." (PMID 33117715, 2020). "In this work, Rg5 induced autophagy in breast cancer cells, which was demonstrated by the formation of autophagosomes observed by TEM, the upregulation of LC3-II, Beclin-1, Atg5, and Atg12 expression and the downregulation of p62 expression." (PMID 31963684, 2020). "A query for CNAs overlapping BECN1 and/or BRCA1 in ovarian cancer and breast cancer confirmed that BECN1 is occasionally exclusively deleted (no co-deletion of BRCA1, 8 of 594 tumors for ovarian cancer and 4 of 1085 for breast cancer)." (PMID 31923184, 2020). "Silibinin is reported to induce autophagy in HeLa cervical carcinoma, and MCF-7 breast cancer cells by the formation of LC3-II, Atg12-Atg5, and also upregulating Beclin-1." (PMID 32121322, 2020). "In breast carcinoma cell line MCF7, it has been established that Beclin-1 expression is below detectable limits, and transfection of the Beclin-1 gene upregulates autophagy." (PMID 32998777, 2020). "We also found that both BECN1 and CDK1 are upregulated in breast cancer tissue compared with normal tissue." (PMID 32802407, 2020). "In both SOC (OV) and breast cancer (BRCA), the frequency of monoallelic deletions of either BECN1 or BRCA1 was >10-fold that of the frequency of single-nucleotide variant or insertion-deletion mutations." (PMID 31923184, 2020). "Multiple breast cancer cells, MDA-MB-231, SUM149, MDA-MB-468, and SUM159 showed increased expression of pATG1, ATG5, ATG7 and BECN1 proteins in a temporal manner in response to HNK treatment." (PMID 32963809, 2020). "Hence, BECN1 may regulate breast cancer initiation through an autophagy-independent pathway." (PMID 33224954, 2020). "Two other studies reported that deletion of some other key autophagy genes, FIP200 or BECN1, led to increased CXCL10 production in mammary tumor cells or melanoma cells." (PMID 32582551, 2020). "In this study, we demonstrated that metronomic chemoendocrine therapy increased the expression of autophagy-related markers, beclin 1 and LC3, and the expression of apoptosis-related markers, TUNEL and M30, in HR-positive breast cancer tissues." (PMID 30813476, 2019). "We also found that LA can increase autophagy through regulation of ATG5, LC3B, and Beclin 1 expression, influencing the proliferation of MDA-MB-231 breast cancer cells." (PMID 30841634, 2019). "Preclinical studies have shown that inhibiting autophagy via siRNA against beclin 1 and ATG5, or pharmacological inhibitors such as 3-MA, increase the efficacy of radiotherapy in breast cancer, glioma, colorectal, and oesophageal cancer cells." (PMID 29679028, 2018). "Compared with Mock groups, the tube sprouting rates were 2~3 times higher in Beclin-1 silenced groups, which further proved that ICJ-mediated autophagy was responsible for the inhibition of breast cancer angiogenesis." (PMID 29403376, 2017). "Recently revealed that PPARγ activation depend on autophagy, since GW9662 was able to prevent the upregulation of Beclin-1 as well as the accumulation of LC3 and MDC labeled vacuoles in breast cancer cells." (PMID 28460464, 2017). "The mRNA expression patterns of BECN1, ATG16L1 or SQSTM1 were also compared across different breast cancer subtypes." (PMID 28628113, 2017). "In conclusion, the epigenetic downregulation of a tumor suppressor gene, Beclin-1, by EHMT2, occurs in breast cancer cell lines." (PMID 27174920, 2016). "Herein, we characterize the epigenetic regulation of Beclin-1 by EHMT2 and nuclear factor-kappa B (NF-κB) and suggest that it exhibits a relationship with tumorigenesis and patient prognosis in breast cancer." (PMID 27174920, 2016).
breast carcinoma (continued). "Our findings indicated that high EHMT2 and low Beclin-1 expression correlated with reduced overall and recurrence-free survival in patients with breast carcinoma in the UNC and NKI breast cancer datasets." (PMID 27174920, 2016). "Recently, Han and colleagues identified potential interaction between Beclin-1 and HER2 in HER2-overexpressing BT-474 and SKBR3 breast cancer cells." (PMID 25580621, 2015). "As expected due to their close proximity on chromosome 17q21, BECN1 and BRCA1 are often concordantly deleted or amplified in breast cancers." (PMID 25825707, 2015). "Regardless of the precise mechanisms by which the Beclin 1 S90A mutation blocks the tumor suppressor function of Beclin 1, our data show a strong association between decreased autophagy, increased tumor growth, and increased cellular proliferation in human mammary tumor xenografts." (PMID 25693418, 2015). "Using tissue microarray sections generated from 740 cases of breast cancer, we performed immunohistochemical staining for Glut-1, CAIX, MCT4, ATP synthase, glutaminase, BNIP3, Beclin-1, LC3A, LC3B and p62." (PMID 24020991, 2013). "In the present study, we detected the mRNA and protein expression levels of beclin 1 and explored the possible effects of DNA methylation and LOH on decreased gene expression in breast cancer tissues." (PMID 20230646, 2010). "We report the roles of BCL2L2 (BCL-W), BCL2, and Beclin-1 (BECN1) in affecting responsiveness to ICI-resistance, and describe how anti-apoptotic BCL2 family members are involved in determining breast cancer cell fate." (PMID 20062536, 2010). "In contrast, genetic depletion of BECN1, ATG5, p62/SQSTM1, or LAMP1 or pharmacological inhibition by chloroquine, resensitizes breast cancer cells to PARPi by shifting DNA repair towards error‐prone NHEJ (non‐homologous end joining), leading to mitotic catastrophe and genomic instability." (PMID 41329030, 2025). "In addition, ectopic overexpression of BECN1 in human breast cancer cell line (MCF7 cells), which have very low levels of endogenous Beclin-1, resulted in activation of autophagy, which concurred with reducing proliferation and inhibiting tumorigenesis." (PMID 40248706, 2025). "Furthermore, in lung and breast cancer, the interaction between MIR30A and BECN1 has been described as another connection between cancer and autophagy." (PMID 37589496, 2024). "Later studies revealed BECN1 is adjacent to breast cancer 1 (BRCA1) on chromosome 17q21, and BECN1 deletion does not occur independently of BRCA1, indicating BRCA1 loss is the primary mutation responsible for breast cancer development." (PMID 38741166, 2024). "Our previous study reported that Beclin 1-targeting stapled peptides induced necrotic cell death but not apoptosis in HER2+ breast cancer cells." (PMID 37598181, 2023). "Recent literature reports the chief role of the BECNI gene encoding Beclin-1 as a tumor suppressor, which has been observed by the absence of Beclin-1 in ovarian, prostate, and breast cancer." (PMID 37893079, 2023). "A study conducted by Zhang and group showed that the knockdown of lncRNA differentiation antagonizing non-protein coding RNA (DANCR) promoted autophagy and apoptosis and inhibited breast cancer cell proliferation by increasing Caspase 3 and 9, Atg5, LC3B, and Bax/Bcl-2 while decreasing Beclin-1." (PMID 36899946, 2023). "NUPR1 could also active autophagy and bind to the promoter regions of some autophagy-related genes, such as BECN1, GREB1, RAB31, PGR, CYP1B1, thereby regulating breast cancer metastasis and transcription." (PMID 37626099, 2023).
breast carcinoma (continued). "Moreover, LC3-II, BECN1 and ATG7 are significantly upregulated by resveratrol in breast cancer cells in a dose-related mode." (PMID 36497321, 2022). "This study’s main objective is to assess the prognostic role of TFEB, CARM1, SIRT1, and Beclin-1 in chemo-treated breast carcinoma and compare the TFEB, CARM1, SIRT1, and Beclin-1 expression with the methylation of PITX2 in breast cancer treated with chemotherapy." (PMID 34663249, 2021). "HER2+ breast cancer cells as well as xenografts derived from them are able to induce autophagy upon Lapatinib treatment, and this correlates with inhibition of HER2 phosphorylation, disruption of the HER/Beclin 1 complex and induction of autophagy." (PMID 33287140, 2020). "Autophagic cell death has been reported in breast cancer cells where cells undergo autophagy as a prerequisite to apoptosis either via canonical pathway involving BECN1 or noncanonical pathway independent of BECN128." (PMID 32963809, 2020). "Paratocarpin E, a prenylated chalcone, can induce apoptosis via the intrinsic pathway and activate autophagy by increasing autophagic vacuoles and upregulating autophagic proteins Beclin-1 and LC3-I/II via the p38/ERK/JNK pathway in human breast cancer MCF-7 cells." (PMID 33415148, 2020). "In the breast cancer MCF-7 cell line, inhibition of autophagy using 3-MA also potentiated the antiproliferative effect of HDACi, such as CTS203, and promoted apoptosis via the CASPASE 8-mediated cleavage of BECLIN-1." (PMID 31861179, 2019). "HER2 has been shown to bind to Beclin 1 and to inhibit autophagy in HER2+ breast cancer cells." (PMID 31877888, 2019). "The beclin 1-independent pathway was determined to be a noncanonical autophagy pathway in human breast cancer cells treated with resveratrol." (PMID 29707130, 2018). "We report for the first time that Beclin 1 level is positively correlated with HER2 expression level in ER-positive breast cancer tissues but not ER-negative ones." (PMID 28881721, 2017). "miR-20a expression correlates negatively with that of BECN1, ATG16L1 or SQSTM1 in breast cancer." (PMID 28628113, 2017). "For example, resveratrol-induced autophagy in human breast cancer cell was independent of Beclin 1 but dependent on ATG7 and ATG12–ATG5." (PMID 28881721, 2017). "Our finding that EHMT2 is overexpressed in breast cancer cells suggests that the development of a novel EHMT2 inhibitor may provide a mechanism for activating an autophagy initiating gene, Beclin-1, in cancer cells." (PMID 27174920, 2016). "Moreover, downregulation of beclin-1 decreased DDR2 expression, which was recently shown to be critical for stabilizing SNAIL1 to promote breast cancer invasion and lymph node metastasis." (PMID 25955408, 2015). "Such a discovery is not without precedent, since evidence of Beclin-1-independent autophagy has been emerging and is documented in neuronal, macrophage, and breast cancer cells." (PMID 26239434, 2015). "To interrogate the effects of BECN1 and BRCA1 in breast cancer, we studied their mRNA expression patterns in breast cancer patients from two large datasets: The Cancer Genome Atlas (TCGA) (n = 1067) and the Molecular Taxonomy of Breast Cancer International Consortium (METABRIC) (n = 1992)." (PMID 25825707, 2015). "Interestingly, Beclin 1 was also found to localize at the intercellular bridge in the control cell line HCC-1395, whereas in the FYVE-CENT R1945Q mutant breast cancer cell line this localization was significantly reduced." (PMID 21455500, 2011). "Both Beclin 1 and FYVE-CENT were found to be downregulated in advanced breast cancers." (PMID 21455500, 2011). "Interestingly, BECN1 knockout did not sensitize MCF-7 cells to talazoparib, indicating that BECN1 is unessential for talazoparib-induced autophagy in MCF-7 breast cancer cells." (PMID 37304006, 2022).
breast carcinoma (continued). "In breast cancer, induction of EMT by overexpression of transcription factor SNAIL can render breast cancer cells resistant to the cytotoxic effect of CD8+T cells through the induction of autophagy; and targeting an autophagy inducer (BECN1) restored CD8+T mediated tumor cell lysis." (PMID 36463238, 2022). "Therefore, the present study aimed to evaluate the modulatory effect of regorafenib on the P2X7/HIF-1α/VEGF, P2X7/P38, P2X7/ERK/NF-κB, and P2X7/beclin 1 pathways on the MCF7 breast cancer cell line and its impact on different signaling pathways involved in breast cancer progression." (PMID 34940128, 2021). "For example, in non–small lung carcinoma, melanoma, and breast cancer, NANOG induces autophagy under hypoxia conditions in CSCs by direct regulation of BNIP3, a protein that interacts with Bcl-2 and mediates the disruption of the Bcl-2/Beclin-1 interaction, promoting tumor cell immune resistance." (PMID 33194736, 2020). "Although the dependence of resveratrol-induced autophagy on Beclin-1 in ESCC cells has not been tested, it is possible that Beclin-1 may be dispensable for this response, as has been demonstrated in breast cancer cells." (PMID 31683722, 2019). "Further experimental studies have found that ERS induction, in turn, induced autophagy and apoptosis in breast cancer cell lines under the regulation of the Akt/mTOR pathway and IRE1/JNK/beclin-1, with the authors suggesting that ERS promotion in breast cancer may be a therapeutic target of TNBC." (PMID 27494867, 2016). "In conclusion, the results from this study indicate that stromal beclin-1 expression could be a potent molecular target in the absence of beclin-1 expression in breast cancer cells." (PMID 25955408, 2015). "However, our findings indicate that decreased BECN1 (but not decreased BRCA1) expression characterizes breast cancers that have aggressive molecular and clinical characteristics." (PMID 25825707, 2015). "Our data showed that beclin 1 expression was significant higher in the BRCA1 positive tumors than in the negative ones, suggesting beclin 1 expression may be related to cell growth in breast cancer." (PMID 20230646, 2010). "Autophagy is required for the hemostasis of cell to prevent tumorigenesis, and absence of autophagy master genes, such as Beclin-1, ATG5, and UVRAG, has been reported in multiple cancers including breast cancer lung cancer." (PMID 34475961, 2021). "Moreover, autophagy, independent of Beclin 1 (BECN1), is a survival mechanism inducing dormancy in breast cancer cells." (PMID 39605887, 2024). "BECN1 knockdown, in combination with BCL2+BCL-W co-inhibition, inhibited autophagy, restored ICI sensitivity, and increased apoptosis (but not necrosis) in ICI treated antiestrogen-resistant breast cancer cells." (PMID 20062536, 2010). "Our previous study reported that Beclin 1-targeting stapled peptides, including Tat-SP4 and another similar peptide with (i, i + 4) linkage for the hydrocarbon staple induced non-apoptotic cell death in NSCLC, breast cancer cells and hepatocellular carcinoma (HCC) cells." (PMID 36765914, 2023).